AREG (amphiregulin)
Diseases named in the same sentence as AREG in open-access papers (continued):
Sharing a sentence is not in itself a finding about the gene and the disease.
Parkinson disease (1 paper, 2023). A progressive degenerative disorder of the central nervous system characterized by loss of dopamine producing neurons in the substantia nigra and the presence of Lewy bodies in the substantia nigra and locus coeruleus. "On western blotting, this group further showed a significant increase of Amphiregulin protein expression relative to the Parkinson's disease group injected with normal saline only (p = 0.0003, t = 11.85, df = 4)." (PMID 37101388, 2023).
periodontitis (1 paper, 2021). An acute or chronic inflammatory process that affects the tissues that surround and support the teeth. "In periodontitis, we observed the emergence of one fibroblast-like population highly enriched in pro-inflammatory genes such as AREG." (PMID 33393902, 2021).
peripheral arterial disease (1 paper, 2025). A disorder of the arteries supplying the upper and lower extremity and the visceral organs. "In both murine and human models of peripheral arterial disease (PAD)—a condition associated with severe ischemic muscle injuries, Tregs potentiated neovascularization through upregulation of IL-10 and amphiregulin expression." (PMID 41459488, 2025).
polyposis (1 paper, 2023). "Taken together with the current findings showing increased IL-33 and AREG expression in Rbm47-IKO mice, we propose that these adaptations might plausibly protect against intestinal injury and inflammation-associated tumorigenesis while promoting spontaneous polyposis." (PMID 37014710, 2023). "We observed upregulation of the IL-33/AREG axis in Rbm47-IKO mice, a pathway previously shown to promote polyposis in ApcMin/+ mice." (PMID 37014710, 2023).
Portal vein thrombosis (1 paper, 2019). Thrombosis of the portal vein and/or its tributaries, which include the splenic vein and the superior and inferior mesenteric veins. "Our study revealed a significant relation between serum AREG level and portal vein thrombosis as well as metastasis in HCC patients." (PMID 31649806, 2019). "On the other hand, serum AREG showed a significant relation to portal vein thrombosis and metastasis." (PMID 31649806, 2019). "AREG showed a significant correlation with portal vein thrombosis and tumor metastasis in HCC patients." (PMID 31649806, 2019).
primary biliary cirrhosis (1 paper, 2025). "In addition to being affected by blood flow, cholestatic liver injury, such as primary biliary cirrhosis and primary sclerosing cholangitis, increase expression levels of AREG to protect liver cells from damage." (PMID 40083329, 2025).
prostate adenocarcinoma (1 paper, 2024). "Another study showed that AREG expression in the prostate gland gradually increases from benign to malignant stages, suggesting that AREG may contribute to the development of prostate adenocarcinoma." (PMID 39451251, 2024).
pterygium (1 paper, 2021). A wedge-shaped fibrovascular lesion arising from the bulbar conjunctiva and extending to the cornea. "This analysis suggests AREG, AREGB and HBEGF produced by epithelial cells are the main upstream regulators driving epithelial cell proliferation in pterygium." (PMID 34769520, 2021). "Based on their upregulation, AREG, AREGB and HBEGF produced by epithelial cells appeared to be driving epithelial cell proliferation in pterygium." (PMID 34769520, 2021).
pulmonary mucoepidermoid carcinoma (1 paper, 2021). A lung carcinoma characterized by the presence of malignant non-keratinizing squamoid cells, mucin-producing cells and intermediate type cells. "To investigate translation of mucins (MUC) in ADAT-silenced cells, we used a line of human pulmonary mucoepidermoid carcinoma cells (NCI-H292) where MUC production is induced by the epidermal growth factor-like protein amphiregulin (AREG)." (PMID 34125917, 2021).
sarcoidosis (1 paper, 2020). Sarcoidosis is a multisystemic disorder of unknown cause characterized by the formation of immune granulomas in involved organs. "Eight upregulated transcripts were common to sarcoidosis lung granulomas (CSF3, SERTAD1, MMP9, CCL19, BCL3, AREG, PTGS, F3)." (PMID 33276795, 2020).
scleroderma (1 paper, 2021). Scleroderma is a rare autoimmune connective tissue disorder characterized by abnormal hardening of the skin and, sometimes, other organs. "Indeed, single cell analyses indicate that AREG is highly expressed in myofibroblasts, not other types of fibroblasts in scleroderma patients." (PMID 33622407, 2021).
Skin rash (1 paper, 2017). A red eruption of the skin. "Because the association between HGF level and OS of the patients was only significant in patients who had developed EGFRI-induced skin rash, we further analyzed the correlation of the plasma concentrations of HGF and amphiregulin with this rash." (PMID 28456787, 2017).
tongue cancer (1 paper, 2023). A malignant neoplasm affecting the tongue. "The protein levels of XBP1s, AREG and bFGF were evaluated with immunohistochemical staining in the tissues from 88 tongue cancer patients who received cDDP‐based chemotherapy." (PMID 36639835, 2023). "Maybe, we can use Abs against AREG or bFGF to abrogate the NF‐KB signalling triggered by chemotherapy or radiotherapy in tongue cancer organoid model in the future." (PMID 36639835, 2023). "Moreover, we detected increased AREG and bFGF protein levels in the blood of tongue cancer patients with X‐box binding protein‐1 (XBP1) activation in tumours under cytotoxic therapy and found that XBP1 activation is associated with poor prognosis of patients." (PMID 36639835, 2023). "We also found that tongue cancer patients with high AREG or bFGF were more likely to be recurrence." (PMID 36639835, 2023). "However, AREG and bFGF protein levels were highly expressed in only 15 (35.71%) and 19 (45.24%) of 42 tongue cancer tissues with relatively low XBP1s expression, respectively, suggesting a positive correlation between XBP1s and AREG and bFGF protein expression in tongue cancers." (PMID 36639835, 2023).
vasculitis (1 paper, 2025). "Considering macrophages have important functions in KD vasculitis, our objective is to investigate the impact of macrophage‐derived Amphiregulin on KD vasculitis." (PMID 40660822, 2025).
Ventricular arrhythmia (1 paper, 2021). "More importantly, cardiac macrophages exist throughout the myocardium, and our finding that Areg deletion generates substrates for ventricular arrhythmia suggests that macrophages and AREG are required for maintenance of myocardial electrical conduction widely throughout the heart." (PMID 33771995, 2021).
viral bronchiolitis (1 paper, 2021). "Peripheral amphiregulin expression has been previously found associated to repair/remodeling features in other disease settings such as infant viral bronchiolitis." (PMID 33717129, 2021).
tumor (278 papers, 2007 to 2026). "Tumor‐associated NK cells exhibit heightened GR target gene signatures, correlating with AREG upregulation." (PMID 41082397, 2026). "The overexpression of AREG was found in numerous cancers where it was associated with tumor survival and chemotherapy resistance." (PMID 39858101, 2025). "Recent studies have shown that AREG protein expression is associated with the pro‐tumor phenotype in Vδ1 T cells, and our optimized cultured γδ T cells almost completely lacked AREG protein expression." (PMID 40112194, 2025). "Several clinical studies reported the importance of AREG in the progression of breast tumors, as well as its association with tumor aggressiveness and poor prognosis." (PMID 39876971, 2024). "In particular, these highly expressed genes were notably associated with tumor development and metastatic progression, including A2M, AREG, chemokines (iCAFs-S1), BGN, MFAP5, THBS2, and TIMP1 (iCAFs-S2)." (PMID 39323622, 2024). "Further bioinformatic analysis revealed that despite being associated with chemoresistant disease, AREG mRNA levels were significantly (p < 0.05) higher in patients with a higher mutation count and tumor mutational burden (TMB), when stratified by quartile." (PMID 38831884, 2024). "A key finding was the activation of anterior gradient 2, yes-associated protein 1, and amphiregulin in OPA tumor cells, indicating a role for this oncogenic pathway in OPA." (PMID 31434729, 2019). "It is also possible that loss of AREG alters the balance of proliferation between different cell types that can contribute to formation of a tumor." (PMID 30367629, 2018). "In a recent work, EREG and AREG expression has been found to have a strong inverse correlation with methylation and to be inversely associated with right-sided tumor location, CIMP-H status and BRAF mutation." (PMID 34532592, 2018). "Trop2+/AREG+ protein coexpression were associated with Tumor Node Metastasis (TNM) stage (χ2 = 50.345, P < 0.001), tumor size (χ2 = 40.349, P < 0.001), lymph node metastases (χ2 = 26.481, P < 0.001), and distant metastases (χ2 = 8.387, P = 0.039)." (PMID 28256068, 2017). "We found that the expression of AREG/EGFR co-expression were associated with poor tumor differentiation, which is consistent with previous studies." (PMID 27391842, 2016). "Clinical investigation also indicated that increased AREG expression was associated with tumor progression including TNM, invasion, and metastasis, and was correlated with poor survival." (PMID 27713123, 2016). "We also found that AREG/EGFR co-expression was associated with poor tumor differentiation, which is similar to that demonstrated in previous studies." (PMID 27391842, 2016). "In our study, we showed that AREG/EGFR co-expression were associated with poor tumor differentiation." (PMID 27391842, 2016). "Knockdown of AREG alone was associated with a suppression of tumor growth that was similar to that observed with erlotinib treatment of HSC-6 control xenografts." (PMID 27004400, 2016). "In the presence of wild-type KRAS, high AREG mRNA levels were independently associated with 83.0% reduction in the risk of death compared to patients with AREG-low tumours." (PMID 23374602, 2013). "This fact indicates that EREG and AREG expression is not only associated with the likelihood of metastasis but is also involved in tumor progression and biological malignancy." (PMID 22409860, 2012). "AREG–deficient NK cells exhibit enhanced tumor control across multiple cancer models, while elevated AREG expression correlates with poor prognosis in diverse malignancies, establishing NK cell‐derived AREG as a therapeutic target." (PMID 41082397, 2026). "Similarly, cancer-associated fibroblasts and certain tumor epithelial cells exhibit elevated AREG expression, establishing a profibrotic and pro-tumorigenic microenvironment." (PMID 40725192, 2025). "Several lines of previous evidence implicated AREG in tumor development." (PMID 33941851, 2021).
tumor (continued). "Furthermore, AREG is overexpressed in tumor-associated DCs and suppressive/M2 macrophages and has been suggested to play a crucial role in immunosuppression and cancer progression." (PMID 32870822, 2020). "Downregulation of AREG slowed down the tumor growth caused by overexpression of TAZ." (PMID 30911072, 2019). "Furthermore, expression of amphiregulin promoted tumour growth, implicating causal relationship between the expression of IL13Rα2 and amphiregulin." (PMID 30718742, 2019). "In a previous report, we demonstrated that, like the production of the EGFR ligand amphiregulin in K-RAS mutated (K-RASmut) tumor cells, stimulated amphiregulin secretion is also obvious in head and neck squamous (HNSCC) tumor cells overexpressing K-RAS wild-type (K-RASwt)." (PMID 27248324, 2016). "Growth-stimulating effects of ERβ may be due in part to downstream actions that promote VEGF, amphiregulin, and Wnt-10b secretion, other factors associated with tumor promotion." (PMID 25874233, 2015). "To determine whether AREG-associated effects in tumor growth and progression were associated with changes in intravasation and metastasis, we examined metastases in the lungs as well as circulating tumor cells (CTCs) in these animals." (PMID 30367629, 2018). "Consistent with the A375 results, AREG KO NK cells markedly improved tumor control in both models, underscoring AREG function as a conserved negative regulator of NK cell anti‐tumor activity." (PMID 41082397, 2026). "AREG KO NK cells displayed enhanced tumor‐suppressive activity, further inhibiting A375 tumor growth compared with WT NK cells." (PMID 41082397, 2026). "More recently, it has also been demonstrated that radiotherapy induces the expression of amphiregulin (AREG) in tumor cells, which facilitates metastasis through reprogramming myeloid cells towards an immunosuppressive phenotype." (PMID 41375050, 2025). "A disintegrin and metalloprotease 17 (ADAM17), another protein associated with chemoresistance, enhances tumor cell proliferation and survival via the epidermal growth factor receptor (EGFR) pathway by cleaving various ligands such as amphiregulin (AREG)." (PMID 40757000, 2025). "AREG inhibition has been shown to sensitize the fibrotic tumor microenvironment (TME) to chemotherapy, creating synergistic effects when combined with conventional anticancer drugs." (PMID 40725192, 2025). "Similar to the lapatinib treatment, cell proliferation, S-phase induction, cell migration, and tumor growth were suppressed by AREG knockdown." (PMID 40422206, 2025). "On the other hand, other subsets, including human Vδ1 T cells and murine Vγ4 and Vγ6 T cells, promote tumor angiogenesis and immune suppression through the secretion of IL-17 and amphiregulin (AREG), thereby facilitating tumor immune escape." (PMID 41055972, 2025). "One tumor (M15) showed again an upregulation at low entinostat dosages and a subsequently inverse dose-dependence, with AREG overexpression being more profound upon treatment with 1 μM entinostat as compared to 3 μM." (PMID 39864337, 2025). "A recently published paper highlighted that radiotherapy increased AREG expression in tumor tissues, which induced distant metastasis growth by reprogramming EGFR+ mononuclear phagocytes (MNPs) into an immunosuppressive phenotype." (PMID 40725192, 2025). "We found that TGFB1/EGFR, LTA/LTBR, CD46/JAG1, and AREG/EGFR ligand‐receptor pairs were stronger in CD4+ T cell‐Plac1+ tumor cells than in CD4+ T cell‐Plac1− tumor cells, among which LTA/LTBR expression was highly specific for Tregs and Plac1+ cells." (PMID 40056047, 2025). "For five tumors selected based on the availability of sufficient tumor material, AREG upregulation was also studied on the protein level." (PMID 39864337, 2025). "Our results from IHC analysis showed ALDOA expression was positively correlated with CTGF and AREG expression in CRC tumor tissues." (PMID 39755705, 2025).
tumor (continued). "Beyond their modulation of the tumor microenvironment, these macrophages directly stimulate tumor growth and induce epithelial–mesenchymal transition via the secretion of AREG (amphiregulin) and HBEGF (heparin-binding EGF-like growth factor)." (PMID 40092486, 2025). "The inhibition of AREG has been shown to sensitize fibrotic tumor microenvironments to chemotherapy, enhancing combination therapy efficacy." (PMID 40725192, 2025). "Oncogenes such as MYB (myeloblastosis transcription factor), meningioma 1 (MN1), progranulin (PGRN) and amphiregulin (AREG) contribute to abnormal transcriptional activity and tumor progression." (PMID 40628732, 2025). "Comparable to EGFR, an even more profound 20-fold increase of AREG mRNA (left) and 30-fold increase of AREG protein levels was observed in MKN-74 tumor xenograft tissue slice cultures (right)." (PMID 39864337, 2025). "Our findings thus offer a promising starting point for further studies into the modulation of the growth factor and HER receptor ligand amphiregulin by HDACi, also bearing in mind its broad relevance in various different tumor entities." (PMID 39864337, 2025). "The EREG/AREG-EGFR communications serve as a pivotal factor in tumor proliferation and migration in several solid human cancers." (PMID 38600248, 2024). "Immunohistochemical analysis of human ESCC tissues showed a positive correlation between the intensity of AREG expression at the tumor-invasive front and the expression level of the CAF marker FAP." (PMID 39451251, 2024). "In this present investigation we first sought to specifically uncover how elevated AREG expression impacts tumor intrinsic immune changes." (PMID 38831884, 2024). "Collectively, these studies show that increased AREG dampens PBMCs’ ability to promote tumor cell death potentially through the reduction of cytokines crucially responsible for carrying out cytotoxic immune responses." (PMID 38831884, 2024). "Increased expression of AREG can potentially enhance cell growth and angiogenesis, thereby promoting tumor progression and reducing overall survival in patients with BC." (PMID 38532419, 2024). "Considering that the αvβ3 integrin plays an important role in tumor metastasis, this study investigated the involvement of these pathways in mediating the triiodothyronine (T3) effects on amphiregulin (AREG) expression." (PMID 39876971, 2024). "While this to the best of our knowledge is the first study to identify the relationship between AREG and IL-5 in the context of tumor immunology, it is known that AREG is expressed by human eosinophils in response to IL-5 exposure." (PMID 38831884, 2024). "In subcutaneous MLS cell line xenograft models, AR30 resulted in partial tumor growth inhibition (TGI) and synergized with cisplatin to significantly reduce tumor growth in part attributable to cisplatin-mediated AREG upregulation." (PMID 40727266, 2024). "Previous studies have linked AREG with the activation of regulatory T cells that accumulate around tumor cells at the time of tumor development, suggesting a role for AREG in carcinogenesis." (PMID 39451251, 2024). "While much is known about AREG’s role in oncogenesis and classical immunity, it is function in tumor immunology has been comparatively understudied." (PMID 38831884, 2024). "For CD14+ monocytes, the VEGFA/PGF-VEGFR1 axes play a significant role in tumor angiogenesis, and the EREG/AREG-EGFR communications serve as a critical factor in tumor proliferation in several solid human cancers." (PMID 38600248, 2024). "While AREG’s role in classical immunity has been well defined, its specific function in the context of tumor immunology has been comparatively understudied." (PMID 38831884, 2024). "Amphiregulin plays key roles in host resistance and tolerance, tissue repair, homeostasis maintenance, local inflammation suppression, and tumor microenvironment immune suppression." (PMID 39687011, 2024).